CRP (C-reactive protein)
Diseases named in the same sentence as CRP in open-access papers (continued):
Sharing a sentence is not in itself a finding about the gene and the disease.
leukocytosis (continued). "The diagnosis of this clinical entity is based on laboratory tests (notably leukocytosis with neutrophilia), elevated acute phase reactants such as CRP and fibrinogen, and radiological imaging test, with cervico-thoracic CT with intravenous contrast being the test of choice." (PMID 36173718, 2023). "In univariate logistic analyses, in-hospital mortality was associated with severe acute cholangitis, PTBD as an initial biliary drainage method, positive blood culture, ICU admission, prolonged LOS, high SOFA score, leukocytosis, elevated CRP, prolonged PT-INR, and elevated creatinine levels." (PMID 38138274, 2023). "Leukocytosis with a left shift and elevated CRP levels were also present in some cases, which might be associated with hemoperitoneum, more severe intramural hematoma, or even perforation into the lumen or out of the serosa of the GI tract." (PMID 37176534, 2023). "However, initial laboratory exam reported mild leukocytosis of 10.00 × 109/L combined with elevated C-reactive protein (CRP) of 59.29mg/L and ProCT of 1.040 ng/mL, hinting potential infectious risks." (PMID 38134096, 2023). "Clinically, endometrioma rupture may mimic the rupture of a hemorrhagic ovarian cyst with findings ranging from symptoms of inflammation, such as fever, leukocytosis, and elevated c-reactive protein, to acute abdominal pain and signs of hypovolemic shock." (PMID 37222834, 2023). "Significant labs included leukocytosis and elevated C-reactive protein." (PMID 37987403, 2023). "Fourteen studies reported elevated CRP (> 5 mg/L) and eleven studies reported leukocytosis." (PMID 37980513, 2023). "Sex, nationality, (migratory) right iliac fossa pain, nausea and vomiting, right iliac fossa tenderness, Rovsing's sign, leukocytosis, shift to the left of neutrophil, and CRP concentration were shown to differ significantly (P < 0.05) between the positive and negative pathology results." (PMID 37951984, 2023). "Furthermore, univariate logistic regression revealed that NLR ≥ 2 and lymphopenia at the 7th DOH, and neutrophilia, leukocytosis, and CRP > 100 mg/L at admission and at the 7th DOH were significantly associated with the risk of death, MV and ICU treatment." (PMID 36016322, 2022). "Interestingly, association with poor functional outcome and mortality was even stronger in patients with leukocytosis and elevated CRP." (PMID 35622132, 2022). "This is commonly followed by leucopenia, leukocytosis and possible increased C-reactive protein." (PMID 36552922, 2022). "Blood reports show elevated leukocytosis and raised C reactive protein (CRP) levels." (PMID 36340521, 2022). "Laboratory abnormalities were common in KD patients; depending on the time of the disease, an increase in ESR and CRP, leukocytosis with neutrophilia is predictable in these patients, although some patients may show different results." (PMID 36714641, 2022). "Laboratory assessment of patients indicated that elevated C-reactive protein (CRP) (>100 mg/L) (33.1%), high ferritin (>500 ng/mL) (18.2%), lymphopenia (<800 cells/μl) (16%), leukocytosis, and increased D-dimer (>1,000 ng/ml) (13.2%) were the most common findings." (PMID 35875562, 2022). "Compared with the subjects with “Near MIS-C” and those with alternative diagnoses, subjects with typical MIS-C presentation had higher leukocytosis, platelet counts and acute inflammatory markers, specifically C-reactive protein (CRP), erythrocyte sedimentation rate (ESR), ferritin and D-dimer." (PMID 36683795, 2022). "This difference was even more pronounced in the subgroup of patients with combined leukocytosis and elevated CRP (median NIHSS 12 vs 8) suggesting that the extent of brain injury might — at least partly — be reflected by inflammatory parameters." (PMID 35622132, 2022). "Besides, hematological changes involved 16 cases with elevated C-reactive protein (CRP) levels (66.7%), 13 cases with neutrophilia (54.2%), and 12 cases with leukocytosis (50.0%)." (PMID 36225778, 2022).
leukocytosis (continued). "He had tachycardia (130 beats/min), hypotension (90/60 mm Hg), leukocytosis (19.4 × 103/μL, 92% neutrophils), anemia (hemoglobin 11 g/dL), thrombocytopenia (72,000/μL), and elevated C-reactive protein (334 mg/L), Pro-Brain Natriuretic peptide (17,768 pg/mL), troponin (0.248 μg/L)." (PMID 35320702, 2022). "However, the most reliable SARS‐CoV‐2 indicators among pregnant women were the followings: the elevated C‐reactive protein (CRP), leukocytosis, and an increased neutrophil ratio." (PMID 35979383, 2022). "His ESR was normal, CRP was elevated (27 mg/L), and he had leukocytosis (21,000/μL)." (PMID 35975181, 2022). "High CRP levels, leukocytosis, and thrombocytosis are well-known markers of active IBD." (PMID 36235613, 2022). "Second, postoperative inflammatory response syndrome may occur after aortic stent graft procedures and hepatic artery chemoembolization, which is characterized by fever, leukocytosis, and elevated C-reactive protein (CRP) and other inflammatory markers." (PMID 35295325, 2022). "However, she remained under surveillance, since she presented a dimer D elevation of 7.70 μg/mL, leukocytosis with 18,890 cells/μL, C-reactive protein (CRP) of 8.8 mg/L, and bilateral wheezing." (PMID 36135686, 2022). "Concomitant changes in MMP-9 or YKL-40 may suggest remodeling or ongoing inflammation, yet most of the markers of acute inflammation (IL-6 and IL-8) resolved, while others persevered (CRP, leukocytosis)." (PMID 36271425, 2022). "The rats treated using vancomycin still showed several impacts, including microcytic hypochromic anemia, thrombocytopenia, leukocytosis, neutrophilia, and increased CRP level; however, the decrease and/or increase in these parameters were not as high as in the positive control." (PMID 35698524, 2022). "Furthermore, patients in both investigated groups showed an increment of CRP and leukocyte count, however, leukocytosis was more pronounced in patients with ACS." (PMID 35755032, 2022). "Second, we evaluated the prognostic importance of leukocytosis if combined with elevated CRP." (PMID 35622132, 2022). "In our study, we accepted patients who had cholangitis in cases of leukocytosis, elevated total bilirubin, and CRP > ULN if there was no other cause of infection; we also looked for fever (37.8 °C), abdominal pain, and jaundice classical triad." (PMID 36161594, 2022). "An increase in ESR was noted in 82.1% pts, CRP-71.4%, leukocytosis - 39.3%." (PMID 36096831, 2022). "A laboratory examination showed leukocytosis and high C-reactive protein serum." (PMID 36147177, 2022). "Improving leukocytosis and decreasing CRP occurred in the following days." (PMID 36581904, 2022). "In the reported cases, the CRP concentration was approximately two- to fourfold elevated in about 95% of spondylodiscitis patients, and roughly one-third of patients displayed mild leukocytosis, similar to our observations." (PMID 35967370, 2022). "Lymphopenia, leukocytosis (with increased absolute neutrophil counts), eosinopenia, neutrophilia, increased CRP and PCT which reflects a persistent state of inflammation may be related to cytokine storm and cellar immune deficiency induced by virus invasion." (PMID 35677769, 2022). "He had elevated CRP (34 mg/L) and leukocytosis at 17,000/μL." (PMID 35975181, 2022). "Clinically relevant results from blood analysis demonstrated leukocytosis (16.5 × 109 cells/L) with neutrophilia (14.0 × 109 cells/L) and elevated C-reactive protein (CRP; 189 mg/L), suggesting bacterial etiology; procalcitonin (PCT) level was within reference range (0.1 μg/L)." (PMID 36148990, 2022). "There is no specific symptom that could be used to anticipate complicated appendicitis, and diagnostic clues include a longer period of symptoms, diffuse peritoneal signs, high fever, elevated leukocytosis and CRP, hyponatremia, and high ESR." (PMID 36676645, 2022). "Complete blood count revealed Leukocytosis, neutrophilia and an elevated C-reactive protein." (PMID 35251601, 2022).
leukocytosis (continued). "(ii) Neither leukocytosis nor the combination of leukocytosis and elevated CRP was significantly associated with the occurrence of sICH." (PMID 35622132, 2022). "The univariate analysis of the main laboratory parameters revealed a significantly higher frequency of inflammatory syndrome (leukocytosis, elevated C-reactive protein and ferritin) and hepatic cytolysis (elevated transaminases) in the group of patients who were admitted to the ICU (p < 0.05)." (PMID 36294376, 2022). "An initial chest X-ray showed bilateral pulmonary infiltrates, and his laboratory tests showed elevated C-reactive protein (CRP) (66.3 mg/L), elevated D-dimer (241 ng/mL), leukocytosis (10.9 × 103/μL) with neutrophil-to-lymphocyte ratio (NLR) of 9.6, and mild thrombocytopenia (134 × 103/μL)." (PMID 35935779, 2022). "C‐reactive protein (CRP) elevation and leukocytosis remained in three patients." (PMID 35855554, 2022). "However, leukocytosis and high C-reactive protein (CRP) levels predominate during a flare, with normalization between episodes." (PMID 36035053, 2022). "Actually, the elevated WBC, CRP, and leukocytosis reflecting the vascular inflammatory response during the acute stage of illness could provide support for a diagnosis of incomplete KD clinical experience." (PMID 35989868, 2022). "In addition, anemia and leukocytosis are common, as is as an increase in lactate dehydrogenase and C-reactive protein." (PMID 34780010, 2022). "Leukocytosis might be present in excessive inflammation, which also results in much higher ferritin, CRP, and ESR levels among severe cases." (PMID 35943018, 2022). "Other previously reported leukocytosis may occur with neutrophilia and higher level of C-reactive protein (CRP) and leukocytosis level of >25 x109 cells/L was associated with mortality in myocarditis diphtheria." (PMID 33539453, 2021). "In a study in which the same surgical procedure was performed by laparotomy and laparoscopy and compared, analgesics were used less frequently in patients treated with laparoscopic surgery, and leukocytosis and increased CRP were inhibited, shortening the hospital stay." (PMID 35011010, 2021). "The laboratory tests showed leukocytosis, lymphopenia, and elevated C-reactive protein levels." (PMID 34256733, 2021). "Similarly, patients with leukocytosis, hypertriglyceridemia, hyperferritinemia, high D-dimer, CRP, LDH, and abnormal liver function tests showed higher HScore." (PMID 34715834, 2021). "The patient's laboratory findings showed leukocytosis and C-reactive protein elevation." (PMID 33879679, 2021). "An increase in inflammatory markers with leukocytosis (>10 × 109/L) and CRP elevation (>5 mg/dL) may be observed." (PMID 33532496, 2021). "Moreover, laboratory features such as leukocytosis and C-reactive protein (CRP) elevation are variable and inconstant." (PMID 34829349, 2021). "Laboratory evaluation showed leukocytosis and elevated C-reactive protein." (PMID 35106197, 2021). "Other laboratory findings included anemia (hemoglobin: 9.8 g/dL), leukocytosis (leukocytes: 20,900/μL), neutrophilia (neutrophils: 18,580/μL) and lymphopenia (lymphocytes: 5067/μL), and elevated inflammatory markers, including C-reactive protein (34.8 mg/dL) and ferritin (2716.0 ng/dL)." (PMID 34698279, 2021). "Second, the systemic consequences of periodontitis, for instance the leukocytosis and mild anemia, the increase in inflammatory mediators (CRP and cytokines) and harmful consequences for health may place these athletes at higher risk." (PMID 34070244, 2021). "They include symptoms (nausea and vomiting, pain in the right iliac fossa (RIF), migration of pain), clinical signs (rebound tenderness, body temperature), and laboratory values (leukocytosis, C-reactive protein (CRP)) but have different interpretations of these findings and different score values." (PMID 34562994, 2021).
leukocytosis (continued). "The decision to start antibiotics was determined by the presence of increased classical inflammatory markers such as C-reactive protein (OR 2.14, 95% CI 1.91–2.41; p < 0.05), procalcitonin (OR 1.73, 95% CI 1.28–2.35; p < 0.05), or leukocytosis (OR 1.18, 95% CI 1.01–1.38; p < 0.05)." (PMID 34749645, 2021). "Blood count demonstrated leukocytosis and increased C-reactive protein." (PMID 33453464, 2021). "Laboratory markers of inflammation, such as leukocytosis and CRP, were evaluated." (PMID 33532496, 2021). "Blood tests, taken during each of the visits before dose increment, did not reveal electrolyte abnormalities, increased liver enzymes, impaired renal function, elevated non-fasting glucose level or evidence of systemic inflammation (leukocytosis or increased CRP)." (PMID 35046880, 2021). "Immediately a CRP, leukocytosis and ferritin normalization occurred." (PMID 34544497, 2021). "Since leukocytosis is common in splenic infarction patients, an additional test of CRP or other biomarkers directly related to bacterial infection may be of prognostic value." (PMID 34728700, 2021). "Leukocytosis is rare in KT patients developing AA, but CRP result generally elevated." (PMID 34372902, 2021). "The sensitivity of either a high CRP, leukocytosis or neutrophilia was 96%." (PMID 33133811, 2020). "Abnormal biochemical parameters were confirmed in patients with COVID-19 disease, the most common being leukocytosis, leukopenia, lymphopenia, elevated levels of CRP and lactate dehydrogenase, high erythrocyte sedimentation rate (ESR), and abnormal levels of liver enzymes." (PMID 32987852, 2020). "EONS was significantly associated (p<0.05) with clinical characteristics including fever and poor perfusion, tachycardia and respiratory signs, and laboratory characteristics including metabolic acidosis, elevated CRP, leukocytosis/leucopenia, and positive chest x-ray findings." (PMID 32190434, 2020). "On blood workup, there was leukocytosis and raised c-reactive protein (CRP)." (PMID 33052272, 2020). "Laboratory findings revealed 11 leukocytosis (Total reported cases 24), 18 lymphopenia (Total: 28), three thrombocytopenia (Total: 8), 26 elevated C-reactive protein (CRP) and 6 negatives, three elevated aspartate aminotransferase (AST) and 5 elevated alanine aminotransferase (ALT) (Total: 25)." (PMID 32685412, 2020). "The laboratory analyses revealed leukocytosis with elevated C-reactive protein (CRP)." (PMID 33385065, 2020). "Other adverse prognostic factors include fever, abnormal blood test results (elevated inflammatory markers, leukocytosis, thrombocytosis, C-reactive protein, and procalcitonin), increased factors for kidney injury (increased creatinine and hyperkalemia), and lactic acidosis." (PMID 32328096, 2020). "Leukocytosis, leukopenia and/or elevation of C-reactive protein are also commonly seen." (PMID 32878325, 2020). "In addition, leukocytosis was present in 88 patients, and increased CRP and ESR were detected in 150 and 261 patients, respectively." (PMID 33281906, 2020). "Lab results showed neutrophil-dominant leukocytosis and elevated C-reactive protein (CRP) of 15.19." (PMID 32711545, 2020). "However, patients in the death group had more prominent laboratory abnormalities than those in the survival group, such as leukocytosis, lymphopenia, elevated C-reactive protein levels, extended PT time, and elevated D-dimer level (all p < .05)." (PMID 32924707, 2020). "The markers of inflammation were high (CRP 217 mg/L and leukocytosis 34.49 × 109/L), and there were signs of multi-organ failure: elevated liver enzymes (ALT 2.26 μkat/L, AST 4.62 μkat/L), prolonged coagulation (INR 1.76) and respiratory failure with mixed acidosis." (PMID 32189223, 2020).
leukocytosis (continued). "In a similar study, among 203 HPIV-positive patients (aged 1 to 71 months) with LRTI in China, a total of 32 (15.8%) had an underlying disease, 21 patients were preterm and 18 patients needed oxygen support, 47 patients had leukocytosis, and 39 patients had increased CRP and ESR." (PMID 33281906, 2020). "CRP was elevated (160 mg/L), with mild leukocytosis (13 x 10e3/uL) and neutrophilia (83%)." (PMID 32375832, 2020). "Based on data analysis, lymphopenia with 49.8% (95% CI; 30.1-69.6), leukocytosis 47.7% (95% CI; 31.6-64.2), elevated neutrophil ratio 83.7% (95% CI; 72.3-91.0), elevated C-reactive protein 57% (95% CI, 43.7-69.3), and decreased lymphocyte ratio 71.4% (95% CI; 16.4-96.9) were observed in the studies." (PMID 33426411, 2020). "In addition to leukocytosis, acute bouts of exercise have been shown to increase levels of inflammatory mediators substances such as C-reactive protein (CRP) and interleukins 1 and 6 (IL-1, 6)." (PMID 32655413, 2020). "Leukocytosis with left shift and raised C-reactive protein were observed." (PMID 32921316, 2020). "The APP response governs a cascade of pathological responses resulting in leukocytosis, elevation of acute reactive proteins (e.g., D-dimer, CRP, serum amyloid A, interleukins, tumor necrosis factor α), as well as clinical responses (e.g., pyrexia, hormonal alterations, muscle protein depletion)." (PMID 32864251, 2020). "The laboratory profile of this patient suggests that a generalized immune response to SARS-CoV-2 was apparent early, based on the neutrophil-lymphocyte ratio (NLR) and CRP, followed by persistent anemia, leukocytosis and hypoalbuminemia during their hospital stay." (PMID 33062489, 2020). "Laboratory evaluation revealed leukocytosis and elevated C-reactive protein." (PMID 32891177, 2020). "Among other results, the patient has an increased CRP and leukocytosis." (PMID 33192833, 2020). "Follow-up tests were requested, since the patient presented signs of peritoneal irritation, which found leukocytosis, neutrophilia, and thrombocytosis, PCR (C-reactive protein) indicative of bacterial infection; previously requested blood cultures were negative." (PMID 32393165, 2020). "In addition, many patients with COVID-19 sepsis often have leukocytosis with lymphopenia and elevated levels of C reactive protein (CRP) and D-dimer." (PMID 33150765, 2020). "The laboratory profile of this patient suggests that a generalized severe immune response to SARS-CoV-2 was apparent early, based on the neutrophil-lymphocyte ratio and CRP, followed by persistent anaemia, leukocytosis and hypoalbuminemia and neurological manifestations during his hospital stay." (PMID 33062489, 2020). "A total of 53 patients (23.66%) had leukocytosis (>15,000/mm3) at some point during hospitalization The CRP was greater than the reference value (<5) in the first evaluation in 63/90 pregnant women (21.6%) and, in the final evaluation, in 104/164 pregnant women (72.2%)." (PMID 31644662, 2019). "Percutaneous cholecystostomy was effective in reducing leukocytosis, C-reactive protein, and fever." (PMID 30867674, 2019). "Complete blood count showed slight leukocytosis and elevated C-reactive protein." (PMID 31089427, 2019). "Leukocytosis and increased levels of acute-phase reactants (erythrocyte sedimentation rate, C-reactive protein, and fibrinogen) may also be present." (PMID 30733802, 2019). "Inflammatory markers such as CRP and leukocytosis can correlate with clinical morbidity and may indicate poor outcomes." (PMID 31088357, 2019). "Inflammatory marker consisted leukocytosis (82.7%), elevated CRP (68.9%), and elevated PCT (71.4%)." (PMID 31689826, 2019). "Our study has demonstrated the involvement of NLR as a predictor of PIAA in pediatric patients operated for acute appendicitis, with a sensitivity and a specificity superior to those of the laboratory parameters routinely studied, such as leukocytosis, neutrophilia and C-reactive protein." (PMID 31750277, 2019).